MROH6 (maestro heat like repeat family member 6)
Synonyms: C8orf73
Tractability: PROTAC: ubiquitination databases record sites on it.
Gene: Protein-coding gene on chromosome 8 (143,566,192 to 143,572,772, reverse strand). Ensembl gene ENSG00000204839.
Subcellular location (Human Protein Atlas): Nucleoplasm
Genetic constraint (gnomAD): Loss-of-function variants: 63 observed, 55.6 expected, observed/expected ratio (o/e) 1.13, 90% interval 0.92 to 1.4. The synonymous counts are far from expectation, so gnomAD's model fits this gene poorly and the ratio says little. Missense variants: 1,169 observed, 881.78 expected, observed/expected ratio (o/e) 1.33, 90% interval 1.26 to 1.39. Synonymous variants: 566 observed, 393.34 expected, observed/expected ratio (o/e) 1.44, 90% interval 1.34 to 1.54.
Homologues: Orthologues: macaque MROH6 (95% identical), pig MROH6 (82% identical), rat Mroh6 (81% identical), mouse Mroh6 (80% identical), dog MROH6 (79% identical), guinea pig MROH6 (79% identical). Paralogues in human: MROH7 (27% identical), MROH5 (24% identical), MROH1 (23% identical), MROH8 (21% identical), MROH2A (18% identical), MROH9 (18% identical), MROH2B (18% identical), MRO (7% identical).
Diseases named in the same sentence as MROH6 in open-access papers:
MROH6 is named in the same sentence as 5 diseases in open-access papers, as found by Europe PMC text mining. Sharing a sentence is not in itself a finding about the gene and the disease. The quoted sentences say what the papers report.
breast carcinoma (1 paper, 2022). "To obtain evidence regarding the effects of serum factors on the expression of the CanCord34 genes, we examined the effects of serum starvation for 72 h on the levels of EEF1D, TIGD5, C8ORF73/MROH6, and BOP1 in the breast cancer SKBR-3, cervical cancer SiHa, and neuroblastoma IMR-32 cell lines." (PMID 36497066, 2022).
COVID-19 (1 paper, 2024). A disease caused by infection with severe acute respiratory syndrome coronavirus 2. "In contrast, the vaccination analysis identified 162,993 significant CpG sites that were impacted by the COVID-19 vaccines, with cg10675725, annotated to GSDMD and MROH6, showing the strongest association (p-value = 7.42 × 10-20)." (PMID 39744634, 2024).
cancer (1 paper, 2022). A tumor composed of atypical neoplastic, often pleomorphic cells that invade other tissues. "Furthermore, three of the CanCord34 genes, namely MROH6, ZNF623, and CCDC166, have no prior PubMed publications in the context of cancer." (PMID 36497066, 2022).
MROH6 also shares sentences with these, for which no sentence is quoted: cervical cancer (1 paper); neuroblastoma (1).